ADAMTS13 (ADAM metallopeptidase with thrombospondin type 1 motif 13)
Diseases named in the same sentence as ADAMTS13 in open-access papers (continued):
Sharing a sentence is not in itself a finding about the gene and the disease.
ischemic stroke (continued). "Additionally, an imbalance of ADAMTS-13 activity and vWF plasma concentration are risk factors for the development of myocardial infarction, ischemic stroke, pre-eclampsia, malignant (or cerebral) malaria and antiphospholipid syndrome." (PMID 33920144, 2021). "However, the association between ADAMTS13 and other cardiovascular diseases such as AF, HF, ischemic stroke, and VTE has been poorly reported." (PMID 34276770, 2021). "Based on these results, even a mild decrease of ADAMTS13 activity could be a risk factor for ischemic stroke and CHD in general population." (PMID 34819564, 2021). "It is logical to predict that low-level ADAMTS13 is strongly associated with ischemic stroke." (PMID 34276770, 2021). "In recent years, large population-based studies report that low ADAMTS13 activity was correlated with a risk of ischemic stroke and dementia independent of other known demographic and cerebrovascular risk factors, but studies on the relationship between ADAMTS13 activity and CSVD are little." (PMID 34690744, 2021). "Besides increasing the risk of developing ischemic stroke, reduced ADAMTS13 activity might also aggravate the progression and outcome of ischemic stroke." (PMID 28591212, 2017). "The von Willebrand factor/ADAMTS13 axis has been shown to play a critical role in thrombotic disorders and in the prognosis of ischemic stroke outcomes." (PMID 40944050, 2025). "In our real-world prospective study, ADAMTS13 activity, VWF: Ag, VWF: Ag/ADAMTS13 Ratio, and their correlations with ischemic stroke severity indices were examined." (PMID 40217918, 2025). "In the experimental study of Zhao and colleagues, it was shown that infusion of recombinant human ADAMTS13 before reperfusion in mice with ischemic stroke resulted in a significantly reduced infarct volume and was associated with improved functional outcomes." (PMID 40217918, 2025). "More data regarding the role of recombinant ADAMTS13 in the management of ischemic stroke are essential to better understand the safety and efficacy of this approach in clinical practice." (PMID 40217918, 2025). "In a mouse model of ischemic stroke, it was shown that ADAMTS13 can dissolve occlusive thrombus, thus facilitating efficient thrombolysis and vessel recanalization." (PMID 41009700, 2025). "This imbalanced vWF/ADAMTS-13 ratio is often observed in conditions like arterial thrombosis, ischemic stroke, pediatric stroke and even myocardial infraction in young women." (PMID 36295093, 2022). "The ADAMTS13 activity and levels are good predictors of the occurrence and prognosis of ischemic stroke." (PMID 35163523, 2022). "Reduced plasma ADAMTS13 and increased plasma VWF are also risk factors for the development of arterial and inflammatory diseases, including myocardial infarction and ischemic stroke." (PMID 33946285, 2021). "There were few animal studies on the relationship between levels of ADAMTS13 and the prognosis of ischemic stroke, though it is widely believed that there is a significant correlation between them." (PMID 31379722, 2019). "Although studies on the efficacy of ADAMTS13 in managing ischemic stroke is still at the stage of animal research, it has shown advantages and is expected to provide a new direction for the treatment of ischemic stroke." (PMID 31379722, 2019). "It is, therefore, logical to anticipate a strong correlation between low levels of ADAMTS13 and the development of ischemic stroke." (PMID 31379722, 2019). "The activity and levels of ADAMTS13 have a good predictive value for the occurrence and prognosis of ischemic stroke." (PMID 31379722, 2019). "A study reported that patients with cardiovascular diseases had a lower level of ADAMTS13 than healthy controls, whereas patients with ischemic stroke had a similar level of ADAMTS13 to healthy controls." (PMID 31379722, 2019).
ischemic stroke (continued). "A prospective case-control study in the UK showed that levels of ADAMTS13 in ischemic stroke or TIA patients who received aspirin were reduced in the early stage (≤4 weeks), but increased to normal later (≥3 months)." (PMID 31379722, 2019). "Based on research findings from in vitro, animal, and clinical studies, we propose that ADAMTS13 is a potential biomarker to guide appropriate treatment for ischemic stroke and a promising therapeutic agent for tPA resistant thrombi." (PMID 31379722, 2019). "Due to the close relationship between levels of ADAMTS13 and the occurrence of ischemic stroke, more and more clinical studies have explored the relationship between levels of ADAMTS13 and the prognosis of ischemic stroke." (PMID 31379722, 2019). "It has been proven that ADAMTS13 is closely related to the occurrence, development, and prognosis of ischemic stroke, protecting the brain from ischemia-reperfusion injury." (PMID 31379722, 2019). "Similar results were found in another study which demonstrated increased levels of inflammatory cytokines and neutrophil infiltration in ADAMTS13−/−mice after ischemic stroke." (PMID 31379722, 2019). "It was reported that the volume of the cerebral infarct was significantly reduced with decreased VWF levels after ischemic stroke, whereas the volume of the cerebral infarct was increased with decreased ADAMTS13 levels." (PMID 31379722, 2019). "The impact of diabetes on the effect of ADAMTS13 on dementia (as well as ischaemic stroke), further emphasises the need to unravel the biological function of ADAMTS13." (PMID 29615758, 2018). "In conclusion, our results show the importance of ADAMTS13 in cerebrovascular disease and put forward the VWF/ADAMTS13 axis as a potential biomarker for ischemic stroke risk and severity." (PMID 28591212, 2017). "Imbalance of the VWF/ADAMTS13 axis has also been suggested to play a role in both ischemic stroke and myocardial infarction (11, –, 14)." (PMID 28209710, 2017). "Three of the analyzed patients (12%) had variants in genes that are not causative mutations but are known risk factors for ischemic stroke; these were mutations in the FV and ADAMTS13 genes." (PMID 40650005, 2025). "ADAMTS13 plays a vital part in the ischemic stroke pathogenesis confirmed by animal and clinical studies, indicating that ADAMTS13 may be a potential therapeutic target." (PMID 34276770, 2021). "Meanwhile, a lower ADAMTS13 activity was causally associated with CHD and MI, while ADAMTS13 activity was not causally related to AF, HF, ischemic stroke, and VTE." (PMID 34276770, 2021). "It has been reported that ADAMTS13 activity could return to normal level in the late phase (≥3 months) of ischemic stroke." (PMID 32849241, 2020). "Whereas ADAMTS-13 activity levels less than 10% can cause TTP, low levels that fall within the normal range (lowest quartile) are associated with increased risk of developing ischemic stroke." (PMID 33352066, 2020). "Furthermore, ADAMTS13 mediated angiogenesis plays an important role in the pathogenesis of ischemic stroke." (PMID 31379722, 2019). "ADAMTS13 is expected to become a new therapeutic agent for ischemic stroke." (PMID 31379722, 2019). "Both animal and clinical studies have demonstrated the important role ADAMTS13 plays in the pathogenesis of ischemic stroke, suggesting that ADAMTS13 might be a promising therapeutic target for ischemic stroke." (PMID 31379722, 2019). "It was speculated that ADAMTS13 might play an important role in counteracting thrombus formation in ischemic stroke." (PMID 31379722, 2019). "In particular, the combination of high amounts of VWF with low levels of ADAMTS13 could form a harmful imbalance for the development of ischemic stroke." (PMID 28591212, 2017). "Moreover, reduced activity of ADAMTS13 toward VWF has been suggested to promote both ischemic stroke and myocardial infarction." (PMID 29326937, 2017).
ischemic stroke (continued). "Indeed, ADAMTS13 seems to play a role in thromboinflammatory diseases like atherosclerosis, myocardial infarction, ischemic stroke, preeclampsia and cerebral malaria." (PMID 27479501, 2016). "In univariate analysis, ADAMTS13 activity during admission was associated with platelet values at the same time point (r = 0.12, p = 0.01) and VWF: Ag levels were associated with age (r = 0.439, p = 0.04), previous ischemic stroke (r = 0.9176, p = 0.031), and glucose levels (r = 0.64, p = 0.049)." (PMID 40217918, 2025). "The risk factors for developing such an ischemic stroke in iTTP patients include older age, comorbid hypertension, and smoking; additionally, high admission plasma levels of anti-ADAMTS13 IgG, but not inflammatory/NETosis markers, are associated with ischemic stroke." (PMID 33458563, 2021). "Also from animal studies, the cerebral infarct volume was significantly increased with lower ADAMTS13 level after ischemic stroke and regional blood flow of the ischemic cortex after reperfusion was significantly decreased in ADAMTS13−/− mice than that in wild-type mice." (PMID 32849241, 2020). "Complete deficiency in ADAMTS13 alone does not lead to ischemic stroke but a prothrombotic state, and the latter may result in ischemic stroke in conjunction with additional genetic or environmental factors." (PMID 31379722, 2019). "Therefore, ADAMTS13 is very likely to become a therapeutic agent for ischemic stroke." (PMID 31379722, 2019). "Considering that plasma levels of ADAMTS13 have been reported to be decreased in patients with myocardial infarction, rs4962153-A may reduce the plasma ADAMTS13 concentration in patients with ischemic stroke." (PMID 22168261, 2011). "We then focused on the relationship between ADAMTS13 and AIS, ranging from ischemic stroke occurrence, to AIS treatment and prognosis." (PMID 31379722, 2019). "Hence ADAMTS13 and VWF could be independent risk factors for ischemic stroke." (PMID 28591212, 2017). "The absence of ADAMTS13 in mice with ischemic stroke has been correlated with increased myeloperoxidase activity and expression of pro-inflammatory cytokines such as interleukin-6 and tumor necrosis factor-α." (PMID 40217918, 2025). "Thus, the aim of this study is to investigate the correlation between ADAMTS13 activity and VWF antigen (VWF: Ag) levels in the outcomes, severity, and disability degree in patients with ischemic stroke." (PMID 40217918, 2025). "The crucial role of ADAMTS13 and VWF has been identified in the ischemic stroke development." (PMID 40217918, 2025). "This case illustrates how TTP can masquerade as ischemic stroke and the application of PLASMIC score without ADAMTS‐13 assay in risk prediction." (PMID 36694637, 2023). "Currently, there is no conclusion on the relationship between ADAMTS13 and the outcome of ischemic stroke." (PMID 31379722, 2019). "This study did not examine the relationship between levels of ADAMTS13 and the prognosis of ischemic stroke patients." (PMID 31379722, 2019). "In addition, animal studies on ADAMTS13 in the treatment of AIS are delivering promising results, especially in the model of conformational activation; as such, ADAMTS13 may become a new therapeutic agent for ischemic stroke." (PMID 35163523, 2022). "Previous studies have shown that ADAMTS13 may become a promising pharmacological agent for ischemic stroke treatment through regulating VWF-mediated inflammation and thrombus formation in addition to its role in angiogenesis, the latter being especially important for ischemic stroke recovery." (PMID 31379722, 2019). "They speculated that the activity of ADAMTS13 can not predict the severity of ischemic stroke." (PMID 31379722, 2019).
myocardial infarction (36 papers, 2008 to 2025). Gross necrosis of the myocardium, as a result of interruption of the blood supply to the area, as in coronary thrombosis. "Previous studies have demonstrated that low levels of ADAMTS13 are associated with an increased risk of myocardial infarction through the influence of lipid levels." (PMID 38643218, 2024). "According to the results of a recent Mendelian randomization study, a lower ADAMTS-13 activity is, moreover, suggested to be causally linked to coronary heart disease and myocardial infarction." (PMID 36703637, 2022). "Plasma ADAMTS13 activity has also been associated with myocardial infarct size and cardiac function after a myocardial ischaemic event." (PMID 34564132, 2021). "The causal effect of lower ADAMTS13 activity on the increased odds of having cardiovascular diseases was coronary heart disease and myocardial infarction." (PMID 34276770, 2021). "In the general population, increased VWF and decreased ADAMTS13 have been associated with myocardial infarction and ischemic stroke, probably by inducing a prothrombotic tendency." (PMID 34134634, 2021). "Lower ADAMTS13 activity was causally associated with the increased risks for coronary heart diseases (b = −0.0041, se = 0.0019, p < 0.05) as well as myocardial infarction (b = −0.0048, se = 0.0022, p < 0.05)." (PMID 34276770, 2021). "A study on mice showed the influence of ADAMTS-13 and vWF deficiency on a myocardial infarction (MI), induced by the ligation of the left anterior descending coronary artery." (PMID 33096906, 2020). "Odds ratios (95% confidence intervals) for risk of myocardial infarction for ADAMTS-13 and von Willebrand factor (VWF), adjusted for three sets of risk factors (I-III), with and without adjustment (+/−Adj)." (PMID 18194418, 2008). "Notably, HIV-associated TTP occurs in the setting of profound CD4 deficiency with altered ADAMTS13 protease activity complicated by myocardial infarction and stroke." (PMID 40362344, 2025). "Prior medical research in cardiology demonstrated that elevated VWF in combination with decreased ADAMTS13 levels is associated with endothelial damage and the development of heart disease, including heart failure, atrial fibrillation, and myocardial infarction." (PMID 40725629, 2025). "Overall, our observations and findings lay the foundation for furthering the prospects of ADAMTS13-based MSC therapy in treating myocardial infarction and other ischemic disorders." (PMID 38177376, 2024). "Age, diabetes mellitus, a history of myocardial infarction, and nicotine consumption had the largest effects on lower ADAMTS-13 values." (PMID 36703637, 2022). "Of note, according to the multivariable linear regression analysis, age, diabetes mellitus, a history of myocardial infarction, and nicotine consumption were likely to have the largest effects on lower ADAMTS-13 activity in both cohorts." (PMID 36703637, 2022). "In line with reports of myocardial infarction and ischaemic stroke, we observed increased risks only in the lower range of ADAMTS13, supporting a threshold effect in ADAMTS13 activity." (PMID 29615758, 2018). "Deficiency or dysfunction of ADAMTS13 due to SNVs may lead to thrombotic pathologies, including TTP, USS, myocardial infarction, and ischemic stroke." (PMID 40362344, 2025). "The pathophysiology of low ADAMTS13 activity being associated with myocardial infarction is not fully understood." (PMID 39274365, 2024). "Increased levels of VWF and reduced levels of ADAMTS13 activity may contribute to the pathogenesis of acute myocardial infarction and might prove to be important mediators of AMI progression." (PMID 32095288, 2020). "Our data suggest that increased levels of VWF and reduced levels of ADAMTS13 activity may contribute to the pathogenesis of acute myocardial infarction." (PMID 32095288, 2020). "It has been reported that the activity of ADAMTS13 is reduced in acute myocardial infarction." (PMID 31379722, 2019).
myocardial infarction (continued). "It has therefore been suggested that circulating levels of ADAMTS-13 may influence circulating levels of VWF and/or its function, and it may therefore influence risk of thrombotic events such as myocardial infarction (MI) in the general population." (PMID 18194418, 2008). "Although she had typical TTP symptoms and elevated cardiac troponin level, ADAMTS13 activity was preserved (34%), leading to the diagnosis of TMA with myocardial infarction." (PMID 36937236, 2022). "Decreased ADAMTS13 and increased VWF levels have been shown to be contributory drivers in myocardial infarction." (PMID 34564132, 2021). "HRP detected by PFA-100 in acute myocardial infarction is reversible by DD of aspirin and clopidogrel; the response is predicted by basal levels of VWF and ADAMTS-13." (PMID 24453831, 2013).